PIK3R2 (phosphoinositide-3-kinase regulatory subunit 2)
Diseases named in the same sentence as PIK3R2 in open-access papers (continued):
Sharing a sentence is not in itself a finding about the gene and the disease.
epilepsy (1 paper, 2021). A brain disorder characterized by episodes of abnormally increased neuronal discharge resulting in transient episodes of sensory or motor neurological dysfunction, or psychic dysfunction. "Although PIK3R2 mutations are known to be responsible for epilepsy-related brain developmental disorders, including MPPH and BPP, there are no reports on the relationship between PIK3R2 mutations and FMTLE." (PMID 34040629, 2021). "In this study, it is the first time for the PIK3R2 mutation (c.265C > T; p.Arg89Cys) to be identified in epilepsy patients and to be found as the potential driver of FMTLE." (PMID 34040629, 2021). "Taken together, the mutations in PIK3R2 and its related signaling pathway are highly associated with epilepsy, suggesting that PIK3R2 may play an important role in the pathogenesis of epilepsy." (PMID 34040629, 2021). "It has been reported by several studies that multiple PIK3R2 mutations are the driving factors of two epilepsy-related developmental brain disorders, megalencephaly-polymicrogyria-polydactyly-hydrocephalus syndrome (MPPH) and bilateral perisylvian polymicrogyria (BPP)." (PMID 34040629, 2021). "In a published summary of 977 epilepsy-related genes found in three databases and recently published papers, PIK3R2 is classified as a neurodevelopmental epilepsy gene associated with brain developmental malformations and epilepsy." (PMID 34040629, 2021). "Since accumulating evidence has revealed that PIK3R2 may be involved in epilepsy pathogenesis, we speculate that PIK3R2 may interact with other epilepsy-related genes." (PMID 34040629, 2021). "However, PIK3R2 mutations have not been reported in non-MPPH or BPP syndromes related to epilepsy thus far." (PMID 34040629, 2021).
Hypertension (1 paper, 2016). The presence of chronic increased pressure in the systemic arterial system. "The most significant interactions for real phenotypes were those between different genes, for example, INS vs. PIK3R2 for DBP, whereas for simulated phenotypes there were significant within-genes interactions such as in INSR gene for SBP, MAP, and hypertension." (PMID 27980660, 2016). "Similarly, the pathway-based 2-locus epistasis analysis indicated significant interactions between INSR and PRKCG for SBP and MAP; INS and PIK3R2 for DBP; PIK3CD and ATP1B2 for hypertension in the real data set." (PMID 27980660, 2016).
Immunodeficiency (1 paper, 2019). Failure of the immune system to protect the body adequately from infection, due to the absence or insufficiency of some component process or substance. "PIK3R2 also interacts with the catalytic active PIK3CD (phosphatidylinositol-4,5-bisphosphate 3-kinase catalytic subunit delta), which is implicated in the phosphoinositide 3-kinase δ syndrome (APDS) associated with senescent T cells, lymphadenopathy, and immunodeficiency." (PMID 31311583, 2019).
intrahepatic cholangiocarcinoma (1 paper, 2023). A carcinoma that arises from the intrahepatic bile duct epithelium in any site of the intrahepatic biliary tree. "have demonstrated that METTL3 promoted apoptosis, autophagy, and pyroptosis of glutamic acid-induced intrahepatic cholangiocarcinoma (ICC) by interacting with DGCR8 and modulating the miR-30b-5p/PIK3R2 axis in an m6A-dependent manner." (PMID 37182154, 2023).
ischemia (1 paper, 2021). A hypoperfusion of the BLOOD through an organ or tissue caused by a PATHOLOGIC CONSTRICTION or obstruction of its BLOOD VESSELS, or an absence of BLOOD CIRCULATION. "miRNA-126 affords its neuro-protective effects against the ischemia injuries by regulating the genes expression like phosphor-inositide-3-kinase regulatory sub-unit 2 (PIK3R2)." (PMID 34044272, 2021). "VCAM-1 as well as PIK3R2 have a relationship to the resistance against endothelial dysfunction and vascular inflammation that have been proposed as the 2 prominent procedures correlated to the neuronal damages of reperfusion or ischemia." (PMID 34044272, 2021).
ischemic disease (1 paper, 2018). Lack of blood supply to an area of the body, resulting in impairment of tissue oxygenation. "Additionally, miR-126 could enhance EPC homing to thrombogenic and ischemic area by targeting PIK3R2 and CXCR4, which plays an important role in the therapeutic effect of EPCs on ischemic diseases." (PMID 29760722, 2018).
ischemic stroke (1 paper, 2024). A stroke disorder caused by obstruction of blood flow to the brain, due to thrombotic (local blood clot formation) or embolic (due to a blood clot or other material traveling from another site) event. "MiR-199a-5p mimic decreased the expression of PIK3R2 and activated Akt signaling pathway after ischemia stroke, reduced the expression of inflammatory cytokines, and attenuated BBB disruption after ischemic stroke." (PMID 39302945, 2024).
Kaposi's sarcoma (1 paper, 2016). A malignant neoplasm characterized by a vascular proliferation which usually contains blunt endothelial cells. "Therefore, our data demonstrated that miR-126-3p is a tumor suppressor miRNA that acts by targeting PIK3R2 in Kaposi's sarcoma cells." (PMID 27191494, 2016).
metabolic syndrome (1 paper, 2023). A cluster of metabolic risk factors for CARDIOVASCULAR DISEASES and TYPE 2 DIABETES MELLITUS. "PIK3R2, STRA8, FLT1, DMRT1, FGF22, NR5A2, and FLT genes were up-regulated in metabolic syndrome after exercise." (PMID 37053002, 2023). "PIK3R2, STRA8, FLT1, DMRT1, FGF22, NR5A2, and FLT were up-regulated and PRDM14, POU5F1, and KDR were down-regulated in metabolic syndrome after exercise." (PMID 37053002, 2023).
metastatic tumors (1 paper, 2022).
MPPH) syndrome (1 paper, 2021). "Megalencephaly-polymicrogyria-polydactyly-hydrocephalus (MPPH) syndrome is caused by mutations, in order of frequency, of either PIK3R2, AKT3, or CCND2 genes with consequent activation of the PI3K-AKT-mTOR pathway." (PMID 35096710, 2021).
periodontitis (1 paper, 2024). An acute or chronic inflammatory process that affects the tissues that surround and support the teeth. "Remarkably, PIK3R2, a PI3K subunit involved in multiple canonical pathways, was downregulated at the mRNA level but was upregulated at the protein level in T2DM-related periodontitis." (PMID 38241313, 2024).
Sepsis (1 paper, 2025). Sepsis is defined as life-threatening organ dysfunction caused by a dysregulated host response to infection. "PIK3R2 was closely related to sepsis and regulated pathological processes in the mechanism of sepsis." (PMID 41293091, 2025).
serous ovarian cancer (1 paper, 2020). "The functional consequences of silencing PIK3R2 were evaluated in three serous ovarian cancer cell lines with high p85β protein levels (OVCAR4, OVCAR8, and SKOV3) using two independent small interfering RNA (siRNA)." (PMID 32385243, 2020).
serous ovarian tumor (1 paper, 2020). "An increased PIK3R2 copy number was detected in 49% of The Cancer Genome Atlas (TCGA) serous ovarian tumor samples (n = 579)." (PMID 32385243, 2020).
undifferentiated thyroid carcinoma (1 paper, 2016). "Moreover, miR-126 has been proposed as a therapeutic agent to treat undifferentiated thyroid carcinoma by targeting the PIK3R2 gene and reducing p85β protein translation while lowering AKT kinase activity." (PMID 27729613, 2016).
vascular malformation (1 paper, 2014). A non-neoplastic disorder that is the result of defects of vascular morphogenesis.
viral infection (1 paper, 2023). "Additionally, autophagy genes IFI16, ZC3H12A, SQSTM1, WDR81, and PIK3R2 are associated with viral infection, including SARS-CoV-1 and were downregulated in this study when cells were treated with NIC." (PMID 37901834, 2023).
tumor (74 papers, 2011 to 2026). "Especially, increased expression of the regulatory subunit PIK3R2 has consistently been associated with an advanced tumor stage and enhanced metastasis formation." (PMID 35192608, 2022). "Interestingly, concurrent PI3K pathway mutations such as PIK3R1/PIK3R2 were recently identified as being involved in HNSCC tumor progression." (PMID 27528217, 2016). "Moreover, COX-2 and PIK3R2 genes are also associated with tumor angiogenesis." (PMID 36910471, 2023). "Conversely, miR-126 acts as a tumor suppressor by inhibiting the expression of the PIK3R2 subunit of PI3K, thereby suppressing the PI3K/AKT pathway and reducing cell proliferation." (PMID 40041495, 2025). "It was validated that SNAI1 facilitates tumor progression and metastasis through the PIK3R2/p-EphA2 axis." (PMID 39702326, 2024). "The sphere formation assay further confirmed that the knockdown of PIK3R2 attenuated tumor stemness." (PMID 39702326, 2024). "Taken together, these results suggest that SNAI1 functionally regulates the expression of PIK3R2, thereby promoting tumor invasiveness." (PMID 39702326, 2024). "miR-126 inhibitors affected the expression of the miR-126 target gene PIK3R2 and reversed the cell cycle arrest and tumor inhibition." (PMID 37854681, 2023). "Phosphoinositide-3-Kinase Regulatory Subunit 1 (PIK3R1) is believed to function as a tumor suppressor, while Phosphoinositide-3-Kinase Regulatory Subunit 2 (PIK3R2) as a tumor driver." (PMID 35395865, 2022). "Among these DETs, multiple genes, including STAT3, PDGFA, PLD2, and PIK3R2, have been reported to be involved in tumor growth." (PMID 35291563, 2022). "Additional pathogenic mutations, including KRAS p.(Ala59Thr), PIK3CA p.(Thr1025Ala), and PIK3R2 p.(Lys564Glu), were identified in that particular stage-3 specimen, suggesting that the tumor is refractory to the anti-HER2 treatment." (PMID 36612265, 2022). "The expression level of multiple genes associated with tumor growth, such as STAT3, PDGFA, PLD2, and PIK3R2, showed a significant decrease." (PMID 35291563, 2022). "We further used the GEPIA database to evaluate the expression differences of PIK3R1 and PIK3R2 between the tumor and the control tissues as the corresponding control data was not available in the TIMER database for some tumors." (PMID 35395865, 2022). "On the other hand, PIK3R2 (phosphoinositide-3-kinase regulatory subunit 2) is a lipid kinase that functions in growth signaling pathways and a known as a tumor suppressor gene." (PMID 31666070, 2019). "In conclusion, PIK3R2 depletion reduced growth of all SQCC tumors with enhanced p85β levels and was sufficient to trigger tumor regression in the six SQCC lines with this phenotype." (PMID 27835880, 2016). "To analyze the status of PI3K pathway in shRNA-treated tumors, we tested extracts from control, PIK3R1 and PIK3R2 shRNA-treated-H226, -CaLu-1 and -H520 tumor samples." (PMID 27835880, 2016). "In particular, interference with PIK3R2 expression triggered tumor shrinkage in all the cell lines with predominant p85β expression." (PMID 27835880, 2016). "As PIK3R2 expression is increased in SQCC tumors, we postulated that interference with PIK3R2 in an established SQCC tumor would halt tumor progression." (PMID 27835880, 2016). "Histological examination of these tumor samples showed a low mitotic index (red arrows), which was even lower after PIK3R2 depletion." (PMID 27835880, 2016). "We next analyzed the effect of depleting PIK3R2 in tumor xenografts from lung SQCC cells with preferential PIK3R2 expression." (PMID 27835880, 2016). "Here we show that PIK3R2 expression is increased in human lung SQCC, and its depletion induced SQCC tumor regression, supporting development of PIK3R2 interfering tools as a therapy for lung SQCC." (PMID 27835880, 2016).
tumor (continued). "To examine the effect of reducing PIK3R2 levels at a cellular level, we prepared a set of xenografts from H226 and CaLu-1 cells and mice were sacrificed at experiment midterm, when the tumor size began to diminish." (PMID 27835880, 2016). "Collectively, these data confirmed that the tumor suppressor function of miR-3151 was mediated via downregulation of PIK3R2 and MADD." (PMID 26517243, 2015). "On the other hand, new miRNA binding sites may be generated, recruiting some tumor-promoting miRNAs to bind to them and indirectly enhancing PIK3R2 expression." (PMID 40725119, 2025). "These biological features suggest that PIK3R2 may modulate the host immune response to tumor antigens and influence the efficacy of immunotherapy such as AFTV." (PMID 40504311, 2025). "Additionally, PIK3R2 facilitates cell cycle progression and proliferation, functioning as a potential tumor-promoting factor." (PMID 40504311, 2025). "Targeting PIK3R2 in combination with therapies that reprogram macrophages could potentially enhance anti-tumor immunity and improve patient outcomes." (PMID 39835132, 2024). "Interestingly Phosphoinositide-3-Kinase Regulatory Subunit 2 (PIK3R2) gene which is considered as tumor driver was hypomethylated (exon/intron region) both in surgical and non-surgical patients." (PMID 38046046, 2023). "Pik3r2 was also identified to be an important proto-oncogene involved in tumor development." (PMID 35468821, 2022). "In contrast to PIK3R1, PIK3R2 was highly expressed in most tumor types, such as BRCA and COAD." (PMID 35395865, 2022). "In contrast, PIK3R2/p85β expression is upregulated in cancer which is regarded as a tumour driver." (PMID 34741385, 2021). "Nonetheless, tumor response to PIK3R2 depletion did not require PIK3CA, PTEN or KRAS mutation, and caused shrinkage of all tumors examined with enhanced p85β expression." (PMID 27835880, 2016). "miR-126-3p is a tumor suppressor miRNA that acts by targeting PIK3R2 in KS cells." (PMID 27191494, 2016). "Moreover, we demonstrate that the interference with PIK3R2 expression in established SQCC xenografts reduces tumor survival." (PMID 27835880, 2016). "Therefore, inhibition of TauT may inhibit the development of tumor by reducing the expression of Pik3r2.In addition, through proteomic analysis, we found that TauT knockout promoted the expression of Lrrc8d protein." (PMID 35468821, 2022). "However, the effect of depletion of PIK3R2 is greater in solid tumors than in cultured cells, hinting that tumor microenvironment may play a role in gene expression." (PMID 35087740, 2021). "We detected two types of response after PIK3R2 depletion, tumors derived from four lines were almost completely eliminated (H2882, H520, H226, CaLu-1), whereas tumor from the other two lines (SK-MES-1, EPLC-272H) showed reduced growth, although the response was not as marked." (PMID 27835880, 2016). "Although tumor response to PIK3R2 depletion required enhanced PIK3R2 expression, the magnitude of the PIK3R2 silencing effect in different tumor cells was not strictly proportional to the p85β expression levels, suggesting that other tumor features modulate this response." (PMID 27835880, 2016). "High PIK3R2 gene expression sustains PI3K pathway activation, promoting T-cell exhaustion and contributing to an immunosuppressive tumor microenvironment." (PMID 40504311, 2025). "PIK3R2 is a key component of the PI3K–Akt signaling pathway, which plays a central role not only in tumor proliferation but also in immune regulation, including T-cell exhaustion, dendritic cell function, and tumor metabolism." (PMID 40504311, 2025).
tumor (continued). "This requires glucose uptake and energy sources for normal cellular response to stress and tumor growth, syndrome development, vascular changes, and megalocephaly (e.g., PIK3R1; PIK3CA; PIK3CG; PIK3CD; PIK3CB; PIK3R3; PIK3R2; PIK3R5; PIK3R6)." (PMID 41010006, 2025). "PIK3R1, which controls cancer cell proliferation, is related to tumor growth and metastasis; PIK3R1 or PIK3R2 plays a role in the pathogenesis of distinct malignancies via common molecular processes." (PMID 36937843, 2023). "Several studies have shown that miR-126 targets include ADAM9, LRP6, PIK3R2, CXCR4, and SLC7A5, all of which participate in the development of diverse tumor types." (PMID 32554852, 2020). "Our findings confirmed that CAPN1/PTPN1 play crucial roles on proliferation, metastasis and erlotinib resistance of LUAD cells as c‐Met/PIK3R2 regulators, and validated the regulatory mechanism of CAPN1 on PTPN1 in tumor model for the first time." (PMID 32395869, 2020). "Knockdown of both PIK3R2 and PIK3CD by over-expression of miR-34a likely affects the anti-tumor response." (PMID 31311583, 2019). "The cliques involving AKT1 (METH), PTEN (mRNA) and AKT1 (METH), PIK3R2 (mRNA) can be construed as tumor suppressing, while cliques involving AKT1 (METH), CCND1 (mRNA) and AKT1 (METH), GRB2 (CN) probably are tumor activating." (PMID 30059495, 2018). "We generated tumor xenografts of SQCC cell lines and examined the consequences of targeting PIK3R2 expression." (PMID 27835880, 2016). "PIK3R2, a key component of the PI3K–Akt signaling pathway, may modulate the host immune response to tumor antigens and influence the efficacy of immunotherapy." (PMID 40504311, 2025). "Additionally, genes typically involved with tumor growth and persistence were downregulated with the addition of ARG2i/COX2i/NOS2i to STING agonism (e.g., Ar, Tgfb3, Tead2, Pik3r2, Jun)." (PMID 38312842, 2024). "Meanwhile, PIK3R2 expression in COAD, KIRC, PAAD, SKCM, UCS (P < 0.05) was associated with tumor stages, but not others." (PMID 35395865, 2022). "CAPN1 enhances the malignant behavior and erlotinib resistance of LUAD cells via degrading PTPN1 and then activating c‐Met/PIK3R2, which suggests CAPN1/PTPN1 may serve as tumor markers or potential targets for diagnosis and treatment of LUAD." (PMID 32395869, 2020). "Their development for PIK3R2 inhibition is justified by the clear potential of PIK3R2 depletion for treatment of lung SQCC tumors as it induced tumor regression without triggering PI3K pathway reactivation." (PMID 27835880, 2016). "Moreover, in addition to p85β (PIK3R2) and Sox2, IRS1, VEGF and CXCR4 have been reported to be target genes of miR-126-3p and to participate in miR-126-3p-induced tumor suppression." (PMID 27191494, 2016). "In HCC15, H2170, PIK3R2 depletion did not affect tumor size." (PMID 27835880, 2016). "The results revealed that PIK3R1 and PIK3R2 showed medium staining in most normal tissues, while in most tumor tissues PIK3R1 showed low or negative staining and PIK3R2 showed medium or high staining." (PMID 35395865, 2022).